OR5B3 (olfactory receptor family 5 subfamily B member 3)
Description:
Odorant receptor.
Synonyms: OR5B13; OST129; OR11-239
Tractability: Antibody: UniProt places it where antibodies can reach, with medium confidence; UniProt predicts a signal peptide or a membrane-spanning region; its Gene Ontology location is reachable by antibodies, with medium confidence.
Gene: Protein-coding gene on chromosome 11 (58,402,464 to 58,406,874, reverse strand). Ensembl gene ENSG00000172769.
Subcellular location: Cell membrane
Pathways (Reactome):
Sensory Perception: Expression and translocation of olfactory receptors
Gene Ontology:
Molecular function: olfactory receptor activity; G protein-coupled receptor activity
Biological process: G protein-coupled receptor signaling pathway; sensory perception of smell; detection of chemical stimulus involved in sensory perception of smell
Cellular component: plasma membrane; membrane
Genetic constraint (gnomAD): Missense variants: 414 observed, 377.55 expected, observed/expected ratio (o/e) 1.1, 90% interval 1.01 to 1.19. Synonymous variants: 144 observed, 135.52 expected, observed/expected ratio (o/e) 1.06, 90% interval 0.93 to 1.22.
Homologues: Orthologues: chimpanzee OR5B3 (95% identical), pig OR5B3 (81% identical), dog OR5B3 (80% identical), mouse Or5b3 (80% identical), dog OR5B3B (78% identical), rat Or5b104 (77% identical), rat Or5b113 (76% identical), mouse Or5b113 (76% identical), rat Or5b3 (76% identical), mouse Or5b104 (75% identical), mouse Or5b111 (75% identical), rat Or5b114 (75% identical), and 19 more. Paralogues in human: OR5B2 (75% identical), OR5B12 (74% identical), OR5B17 (71% identical), OR5B21 (67% identical), OR8U1 (53% identical), OR5AP2 (52% identical), OR5AR1 (51% identical), OR5AU1 (50% identical), OR9I1 (50% identical), OR8U3 (50% identical), OR5A1 (50% identical), OR5F1 (50% identical), and 84 more.